Y_RNA (Y RNA )
Gene: Miscellaneous RNA gene on chromosome 22 (29,758,758 to 29,758,859, forward strand). Ensembl gene ENSG00000200976.
Homologues: Orthologues: chimpanzee Y_RNA (100% identical), macaque Y_RNA (94% identical). Paralogues in human: Y_RNA (88% identical), Y_RNA (86% identical), RNY3 (85% identical), Y_RNA (84% identical), Y_RNA (83% identical), RNY3P1 (82% identical), Y_RNA (82% identical), Y_RNA (81% identical), RNY3P12 (80% identical), Y_RNA (80% identical), RNY3P14 (79% identical), RNY3P16 (79% identical), and 96 more.